RNU6-1050P (RNA, U6 small nuclear 1050, pseudogene)
Gene: Small nuclear RNA gene on chromosome 18 (31,937,533 to 31,937,639, forward strand). Ensembl gene ENSG00000222320.
Homologues: Orthologues: macaque U6 (78% identical), dog U6 (68% identical), rabbit U6 (68% identical), guinea pig U6 (61% identical), guinea pig U6 (60% identical), mouse Gm25269 (60% identical), rat LOC120096466 (59% identical). Paralogues in human: RNU6-944P (83% identical), RNU6-1209P (82% identical), RNU6-380P (82% identical), RNU6-1060P (81% identical), RNU6-336P (81% identical), RNU6-744P (81% identical), RNU6-1243P (80% identical), RNU6-1287P (80% identical), RNU6-1309P (80% identical), RNU6-218P (80% identical), RNU6-43P (80% identical), RNU6-455P (80% identical), and 1283 more.